RIOK1 (RIO kinase 1)
Description:
Involved in the final steps of cytoplasmic maturation of the 40S ribosomal subunit. Involved in processing of 18S-E pre-rRNA to the mature 18S rRNA. Required for the recycling of NOB1 and PNO1 from the late 40S precursor. The association with the very late 40S subunit intermediate may involve a translation-like checkpoint point cycle preceeding the binding to the 60S ribosomal subunit (By similarity). Despite the protein kinase domain is proposed to act predominantly as an ATPase (By similarity). The catalytic activity regulates its dynamic association with the 40S subunit (By similarity). In addition to its role in ribosomal biogenesis acts as an adapter protein by recruiting NCL/nucleolin the to PRMT5 complex for its symmetrical methylation.
Synonyms: RIO1; AD034; FLJ30006; bA288G3.1; RRP10
Tractability: Small molecule: a structure with a bound ligand is known; a high-quality ligand is known; it belongs to a druggable protein family. PROTAC: ubiquitination databases record sites on it; its protein half-life has been measured; a small molecule that binds it is known.
Target class: Protein Kinase; Kinase; Atypical protein kinase RIO1 subfamily; Atypical protein kinase group; Atypical protein kinase RIO family; Enzyme
Gene: Protein-coding gene on chromosome 6 (7,389,467 to 7,418,037, forward strand). Ensembl gene ENSG00000124784.
Subcellular location: Cytoplasm, cytosol
Subcellular location (Human Protein Atlas): Cytosol
Pathways (Reactome):
Metabolism of RNA: Major pathway of rRNA processing in the nucleolus and cytosol
Gene Ontology:
Molecular function: protein binding; protein serine kinase activity; protein serine/threonine kinase activity; ATP binding; ATP hydrolysis activity; catalytic activity
Biological process: maturation of SSU-rRNA; positive regulation of rRNA processing; ribosomal small subunit biogenesis
Cellular component: cytoplasm; cytosol; methylosome; methyltransferase complex; preribosome, small subunit precursor; nucleoplasm
Genetic constraint (gnomAD): Loss-of-function variants: 38 observed, 42.86 expected, observed/expected ratio (o/e) 0.89, 90% interval 0.68 to 1.16. The upper end of that interval is the gene's LOEUF score, 1.16, which puts it in group 5 of 6, group 1 being the genes least tolerant of losing a copy. Missense variants: 404 observed, 448.94 expected, observed/expected ratio (o/e) 0.9, 90% interval 0.83 to 0.98. Synonymous variants: 135 observed, 153.54 expected, observed/expected ratio (o/e) 0.88, 90% interval 0.76 to 1.01.
Homologues: Orthologues: chimpanzee RIOK1 (99% identical), macaque RIOK1 (96% identical), dog RIOK1 (90% identical), guinea pig RIOK1 (88% identical), rabbit RIOK1 (88% identical), pig RIOK1 (86% identical), rat Riok1 (82% identical), mouse Riok1 (80% identical), tropical clawed frog riok1 (70% identical), zebrafish riok1 (68% identical), Drosophila melanogaster RIOK1 (49% identical), Caenorhabditis elegans riok-1 (40% identical). Paralogues in human: RIOK3 (29% identical), RIOK2 (18% identical), ATMIN (15% identical).
Diseases named in the same sentence as RIOK1 in open-access papers:
RIOK1 is named in the same sentence as 41 diseases in open-access papers, as found by Europe PMC text mining. Sharing a sentence is not in itself a finding about the gene and the disease. The quoted sentences say what the papers report.
lung carcinoma (6 papers, 2022 to 2025). "Here, we showed that RIOK1 can cause phenotypic changes such as lung cancer cell proliferation, migration, and invasion, and is accompanied by changes in these phenotypic important executive proteins." (PMID 35281872, 2022). "Previous studies had reported high expression of RIOK1 in various solid tumors, including lung cancer, breast cancer, and prostate cancer." (PMID 39865406, 2025). "Characterization of RIOK in cancer using isogenic colon, breast, and lung cancer cell lines has shown that silencing of RIOK1 inhibited proliferation and invasiveness in 2D and 3D culture systems." (PMID 37298928, 2023). "In lung cancer, RIOK1 is reported to have maintained cell survival and a diminished therapeutic effect of cisplatin, with lower survival in patients with greater RIOK1 expression compared to that in their counterparts." (PMID 37301535, 2023). "In our research, we show that RIOK1 is highly expressed in NSCLC and positively correlated with the malignant progression of lung cancer, and the high expression of RIOK1 indicates a poor prognosis." (PMID 35281872, 2022). "In conclusion, our study for the first time clarified RIOK1 positively correlated with the malignant progression of lung cancer, and the high expression of RIOK1 indicates a poor prognosis." (PMID 35281872, 2022). "RIOK1 is overexpressed in some cancers including colorectal and lung cancer." (PMID 36845147, 2023). "RIOK1 was previously indicated as a direct c-myc downstream target in a lung cancer cell line, which might explain the present pathway-analysis results." (PMID 37301535, 2023). "It is a further step for the research of RIOK1 in lung cancer." (PMID 35281872, 2022). "Among them, we compared the mRNA expression of RIOK1 between lung cancer and normal tissues." (PMID 35281872, 2022). "For example, in non‐small cell lung cancer (NSCLC), high expression of RIOK1 can promote tumor cell proliferation, suppresse apoptosis, and facilitate invasion and metastasis." (PMID 39865406, 2025). "To investigate the functions of RIOK1 in NSCLC, we first used a western blotting assay to detect its expression in lung cancer cell lines." (PMID 35281872, 2022). "RIOK1 has been reported to be highly expressed in non-small cell lung cancer (NSCLC), however, its clinical significance and biological function are still largely unknown in lung cancer." (PMID 35281872, 2022).
breast carcinoma (5 papers, 2022 to 2025). "In HR‐negative breast cancer cells, overexpression of RIOK1 promoted cell growth and invasion by altering PI3K/AKT and MAPK/ERK signaling." (PMID 39865406, 2025). "In HR‐negative breast cancer cells, overexpression of RIOK1 promotes cell growth and invasion by altering PI3K/AKT and MAPK/ERK signaling." (PMID 39865406, 2025). "Over-expression of RIOK1 was further found in HR-negative breast cancer and correlated with advanced stage and poorer breast cancer patient prognosis." (PMID 35281872, 2022). "Overexpression of RIOK1 was shown to promote breast cancer cells proliferation and invasion by regulating the PI3K/AKT and MAPK/ERK signaling pathways in HR-negative breast cancer cells." (PMID 35281872, 2022). "That is consistent with previous studies that the knockdown of RIOK1 significantly rewards the protein level of Cyclin B1 and phospho-AKT in breast cancer cells." (PMID 35281872, 2022). "Whereas in previous reports RIOK1 expression was correlated with hormone receptor status and phosphatidylinositol 3-kinase (PI3K)/AKT signaling in breast cancer and glioma, respectively, no consistent association of RIOK1 mRNA expression with AR and PI3K/AKT target gene sets in PCa was observed." (PMID 37301535, 2023).
glioblastoma (5 papers, 2013 to 2022). The most malignant astrocytic tumor (WHO grade IV). "A previous study reported that RIOK2 formed complexes with RIOK1 and mTOR and then enhanced the Akt-signaling pathway in glioblastoma." (PMID 36661680, 2022). "In addition, RIOK2 and RIOK1 are highly expressed in glioblastoma cells, overexpression of RIOK1/2 promotes cell proliferation, and down‐regulation of RIOK1/2 causes apoptosis and increased sensitivity to chemotherapy." (PMID 32125767, 2020). "A study by Read and colleagues investigated a Drosophila glioblastoma model and discovered the Akt-dependent overexpression of RIOK1 and RIOK2 in glioblastoma cells." (PMID 33383959, 2020). "Our results revealed that the atypical kinases RIOK1 and RIOK2 are overexpressed in glioblastoma cells in an Akt-dependent manner." (PMID 23459592, 2013). "RIOK1 and RIOK2 have been shown to drive proliferation and survival in glioblastoma cells." (PMID 32125767, 2020).
colorectal cancer (4 papers, 2020 to 2025). A primary or metastatic malignant neoplasm that affects the colon or rectum. "In addition, RIOK1 was significantly up‐regulated in colorectal cancer and associated with an aggressive and poor survival." (PMID 32125767, 2020). "The cell lines were treated with Nintedanib, a RIOK1 inhibitor, for 48 h or 72 h, and cell viability was monitored to determine effectiveness; 5FU, the most widely used chemotherapeutic agent for colorectal cancer, and Triton X-100 were used as positive controls." (PMID 37298928, 2023). "For example, RIOK1 promotes growth and metastasis of colorectal cancer cells in vitro and in vivo." (PMID 32125767, 2020). "RIOK1 also cooperated with AKT1 to activate NF‐κB signaling, driving colorectal cancer progression." (PMID 39865406, 2025).
glioma (3 papers, 2021 to 2023). A benign or malignant brain and spinal cord tumor that arises from glial cells (astrocytes, oligodendrocytes, ependymal cells). "In this study, we confirmed that RIOK1 and AKT1 levels significantly increased in GBM tissues and were positively associated with tumor malignancy, while knockdown of RIOK1 inhibits glioma cell growth through AKT1 and c-Myc in vitro." (PMID 34475988, 2021). "Although RIOK1 has been implicated in glioma cell proliferation and invasion, its expression, clinical significance and prognostic role in glioma tissue are still unknown." (PMID 34475988, 2021). "To evaluate the roles of RIOK1 in glioma cells, we first assessed the effect of silencing RIOK1 on glioma cell proliferation (U87 and U251)." (PMID 34475988, 2021). "In vitro studies have shown that the RIOK1-AKT signaling plays an important role in the malignant phenotype of glioma cells." (PMID 34475988, 2021). "According to the MTT growth curves and colony formation experiments, silencing RIOK1 significantly inhibited glioma cell proliferation." (PMID 34475988, 2021). "Consistent with the previous studies, RIOK1 knockdown inhibited glioma cell proliferation, colony formation, migration, and invasion." (PMID 34475988, 2021). "In vitro studies have shown that the right open reading frame kinase 1/protein kinase B (RIOK1-AKT) signaling pathway plays an important role in the malignant phenotype of glioma cells." (PMID 34475988, 2021). "RIOK1 plays important roles in many kinds of tumors, but its expression in different types of glioma cells and its effect on biological behavior are still unclear." (PMID 34475988, 2021). "In vitro experiments showed that silencing RIOK1 inhibited the proliferation, migration, and invasion of glioma cell lines by suppressing AKT and c-Myc expression." (PMID 34475988, 2021). "An oncogenic role of RIOK1 in glioma has been suggested, in which RIOK1 is co-expressed with AKT." (PMID 37301535, 2023). "Indeed, after RIOK1 knockout, c-Myc protein levels were significantly decreased, which inhibits glioma progress." (PMID 34475988, 2021). "Therefore, we silenced RIOK1 expression in U87 and U251 cell lines to clarify the function of RIOK1 in glioma cells." (PMID 34475988, 2021). "Correlation analysis of the western blot data showed that RIOK1 and AKT1 expression were significantly correlated in glioma samples (p<0.001, r=0.7084)." (PMID 34475988, 2021). "Compared with normal tissues, RIOK1 and AKT1 expression were significantly upregulated in glioma tissues." (PMID 34475988, 2021). "This study aimed to investigate the co-expression of RIOK1 and ATK in glioma tissues and its clinical significance." (PMID 34475988, 2021). "RIOK1 and AKT1 protein levels were determined by IHC in 106 glioma and 10 control samples using tissue microarrays." (PMID 34475988, 2021). "It is therefore essential to investigate RIOK1 and AKT1 expression in glioma to identify new therapeutic approaches and prognostic biomarkers." (PMID 34475988, 2021). "Our results demonstrate that RIOK1 and AKT1 expression are upregulated in glioma and correlate with poor prognosis." (PMID 34475988, 2021). "RIOK1 and RIOK2 are also highly expressed in glioma cell lines; overexpressing RIOK1/2 contributes to proliferation, while their knockdown induces apoptosis and renders cells more sensitive to chemotherapy." (PMID 34475988, 2021). "The results showed that RIOK1 and AKT1 protein levels were upregulated in glioma, with the highest expression in high-grade samples." (PMID 34475988, 2021). "RIOK1 and AKT1 mRNA levels were significantly higher in glioma patient tissues compared to normal brain tissues (TCGA-GBMLGG and GTEx databases), and their expression levels were significantly correlated (TCGA-GBMLGG databases, p<0.001, r=0.440)." (PMID 34475988, 2021). "The tissue microarray results showed that RIOK1 and AKT1 expression in glioma tissues were significantly higher than those in matched normal brain tissues." (PMID 34475988, 2021).
heart failure (2 papers, 2019 to 2023). Inability of the heart to pump blood at an adequate rate to meet tissue metabolic requirements. "Different from inhibitors generated from high-throughput screening or de novo design from a single target, it is known that levosimendan interacts with other proteins that are the drug targets for the heart failure than RIOK1." (PMID 31206508, 2019). "Furthermore, it has been predicted that levosimendan, a heart failure drug, could serve as a potential inhibitor of several kinases including RIO Kinase 1 (RIOK1), through ligand-binding site comparison and protein-ligand docking." (PMID 38239190, 2023).
lymphoma (2 papers, 2019 to 2021). A malignant (clonal) proliferation of B- lymphocytes or T- lymphocytes which involves the lymph nodes, bone marrow and/or extranodal sites. "Second, we uncover that RIOK1 and its associated RNA processing pathway is an effective novel target for multiple types of cancers, especially, lymphoma." (PMID 31206508, 2019). "Subsequent experiments and systems biology analyses confirm this prediction, and suggest that levosimendan is active against multiple cancers, notably lymphoma, through the direct inhibition of RIOK1 and RNA processing pathway." (PMID 31206508, 2019).
melanoma (2 papers, 2024 to 2025). A malignant, usually aggressive tumor composed of atypical, neoplastic melanocytes. "In melanoma cells, the elevated genes included MAP2K7, RIOK1, GOPC, KHDC4 and PDPK1, which may be associated with stress/drug resistance, protein synthesis, and the regulation of cellular migration." (PMID 41383633, 2025).
pancreatic cancers (2 papers, 2023 to 2025). "Beyond this general metabolic alteration, MTAP deficiency leads to enhanced expression of hypoxia-inducible factor 1α (HIF1-α) and activation of RIO kinase 1 (RIOK1) in pancreatic cancers, prompting metabolic adaptation towards a glycolytic phenotype and de novo purine synthesis." (PMID 41439984, 2025). "RIO kinase 1 (RIOK1), a kinase upregulated in MTAP-deleted pancreatic tumor cells, could interact with and phosphorylate HIF1α to affect its stability." (PMID 37091983, 2023).
cervical cancer (1 paper, 2024). A primary or metastatic malignant neoplasm involving the cervix. "PRMT5, WD45 and RIOK1 are expressed in different cancer cell lines such as cervical cancer HeLa-CD95 and B lymphoblastoid SKW 6.4 cells." (PMID 38730267, 2024).
colon cancer (1 paper, 2023). "Several reasons lead to the selection of RIOK1 as the target for further investigation, including that RIOK1 was found to be overexpressed in colon cancer cells, which promotes cell proliferation in vitro in human CRC." (PMID 37298928, 2023). "Recent publications have demonstrated an SL role for RIOK1 in methylthioadenosine phosphorylase (MTAP)-depleted cells and its overexpression in colon cancer cells was shown to promote cell proliferation in vitro in human CRC." (PMID 37298928, 2023).
gram-negative bacterial infections (1 paper, 2018). Infections caused by bacteria that show up as pink (negative) when treated by the gram-staining method. "The results demonstrated that the riok-1–p38 MAPK pathway plays an important role in immunity against Gram-negative bacterial infection in C. elegans." (PMID 29719537, 2018).
hepatocellular carcinoma (1 paper, 2025). A malignant tumor that arises from hepatocytes. "Our previous functional experiments demonstrated that RIOK1 plays a pivotal role in promoting the occurrence of hepatocellular carcinoma." (PMID 39865406, 2025). "In this study, we report the role mediated by RIOK1 in hepatocellular carcinoma." (PMID 39865406, 2025).
liver cancer (1 paper, 2025). An epithelial or non-epithelial malignant neoplasm that arises from the liver. "Among them, we compared the mRNA expression of RIOK1 between liver cancer and normal tissues using data from TCGA." (PMID 39865406, 2025).
lymph node metastasis (1 paper, 2022). "To investigate the relationship between the expression of RIOK1 and clinicopathological characteristics in NSCLC patients, we found that the expression of RIOK1 was correlated with pathological grade, tumor size, lymph node metastasis, and survival status of NSCLC (*p< 0.05)." (PMID 35281872, 2022).
non-small cell lung carcinoma (1 paper, 2022). A group of at least three distinct histological types of lung cancer, including non-small cell squamous cell carcinoma, adenocarcinoma, and large cell carcinoma. "In summary, these findings revealed a novel function of RIOK1 in non-small cell lung cancer progression." (PMID 35281872, 2022).
preeclampsia (1 paper, 2025). Preeclampsia is a hypertensive disorder of pregnancy that is characterized by new-onset hypertension with proteinuria presenting after 20 weeks of gestation, and depending on mild or severe forms may initially present with severe headache, visual disturbances, and hyperreflexia. "qRT-PCR confirmed that GLUL and NCL expression decreased and DDX28 and RIOK1 expression increased in clinical placental samples of preeclampsia group." (PMID 40552285, 2025).
prostate carcinoma (1 paper, 2025). A carcinoma that arises from epithelial cells of the prostate gland. "Another report showed that RIOK1 promotes prostate cancer through the c‐myc/E2F pathway." (PMID 39865406, 2025).
sterility (1 paper, 2015). "Worms in which riok-1 was knocked down displayed an oogenesis-specific sterility that was associated with several defects in gonad organisation." (PMID 25688864, 2015). "To establish whether sterility linked to RIOK-1 was due to a defect in spermatogenesis or oogenesis, we knocked down riok-1 in fog-2(q70), which exists as a male and female worms." (PMID 25688864, 2015).